TRPM7 (transient receptor potential cation channel subfamily M member 7)
Diseases named in the same sentence as TRPM7 in open-access papers (continued):
Sharing a sentence is not in itself a finding about the gene and the disease.
breast carcinoma (continued). "TRPM7 has been indicated as a potential therapeutic target for GBM in addition to other cancer types, including: pancreatic cancer, leukemia, head and neck cancer, prostate cancer, retinoblastoma, nasopharyngeal cancer, gastric cancer, ovarian cancer, and breast cancer." (PMID 28061441, 2017). "However, The TRPM7 kinase inhibitor TG100-115 exhibited little impact on the proliferation of MDA-MB-231 breast cancer cells, suggesting that the anti-proliferative effect of TRPM7 silencing is not likely tod be related to the structural domain of TRPM7 kinase." (PMID 40078961, 2025). "However, the exact role played by TRPM7 in breast cancer cell viability has not been explored." (PMID 31947967, 2020). "TRPM7 kinase domain and not Ca2+ influx through the channel was suggested to be involved in breast cell migration via the phosphorylation of myosin IIA in metastatic estrogen receptor (ER) breast cancer." (PMID 38255793, 2024). "Till now, though not as much as those reported in breast cancer cells and osteoclasts, multiple calcium channels have also been reported to modulate osteoblast proliferation, differentiation, migration and mineralization, including TRPV1, TRPV4, TRPM7, TRPP2, Cav1.2, ORAI1/SOCE, P2X1, and P2X7." (PMID 32211326, 2020).
prostate carcinoma (30 papers, 2012 to 2025). A carcinoma that arises from epithelial cells of the prostate gland. "In the context of malignancies, TRPM7 is a Ca2+ and Mg2+ permeable ion channel which is associated with the growth and progression in breast, gastric, pancreatic, and prostate cancers." (PMID 35771152, 2022). "In prostate cancer, high expression of TRPM7 is associated with the migration and invasion of cancer cells." (PMID 36363540, 2022). "The p value of the Kaplan-Meier survival analysis result from HPA was 0.016, suggesting that the high expression of TRPM7 gene in prostate cancer patients was closely associated with poor survival of prostate cancer." (PMID 32215176, 2020). "It suggests that the high expression of TRPM7 is closely associated with the progression of prostate cancer." (PMID 32215176, 2020). "Previous studies have suggested the unique function of TRPM7 in controlling cell migration and invasion of ovarian, breast and prostate cancers, yet the precise underlying mechanisms are largely unknown and may vary depending on cellular context." (PMID 32684624, 2020). "This study, as well as previous researches uses androgen-independent prostate cancer cell lines, which might cause the discrepancy of the effects of TRPM7 in prostate cancer between the HPA database and these in vitro studies." (PMID 32215176, 2020). "Consequently, TRPM7 overexpression is associated with poor survival in prostate cancer patients." (PMID 36158191, 2022). "Transforming growth factor beta (TGFβ), known to promote the metastasis of prostate cancer inducing cell migration, and enhanced TRPM7 expression and function in prostate cancer cells." (PMID 38255793, 2024). "A recent study revealed the mechanism of the involvement of TRPM7 in the growth and metastatic ability of prostate cancer cells under hypoxic conditions." (PMID 38255793, 2024). "Role of the TRPM7 chanzyme in the pathophysiology of prostate cancer, melanoma and multiple myeloma." (PMID 38255793, 2024). "The increased expression of TRPM7 in human prostate cancer cell lines has been repeatedly published." (PMID 38255793, 2024). "The TRPM7 antagonist carvacrol reduced prostate cancer cell proliferation, migration and invasion in prostate cancer cell lines." (PMID 38255793, 2024). "Through the regulation of TRP channels like TRPM2 and TRPM7 in neuronal cells and prostate cancer cells, the RESV therapy altered Ca2+ influx." (PMID 38976129, 2024). "In prostate cancer, it has been described that TRPM7 expression is much higher in metastatic prostate cancer than in benign prostatic hyperplasia." (PMID 37762011, 2023). "Androgen-independent prostate cancer cells also undergo EMT in response to hypoxia via a TRPM7/HIF-1ɑ/Annexin A1 signaling pathway." (PMID 36158191, 2022). "In prostate cancer, cholesterol stimulates Ca2+ influx through TRPM7, which enhances cell proliferation and migration via ERK and Akt phosphorylation, reduces E-cadherin expression, and increases calpain activity." (PMID 36158191, 2022). "Genetic downregulation of TRPM7 was shown to inhibit hypoxia-induced cell motility in androgen-independent prostate cancer cells." (PMID 33726758, 2021). "TRPM7 was shown to affect cancer through its regulation of the epithelial-mesenchymal transition in prostate cancer, ovarian cancer, and colorectal cancer." (PMID 33435261, 2021). "They stated that reduced TRPM7 repress cell migration and invasion in prostate cancer cell lines, while TRPM7 overexpression increased the migration of prostate cancer cells." (PMID 34938330, 2021). "Open access database results showed that high expression of TRPM7 was closely related to the poor survival of prostate cancer patients." (PMID 32215176, 2020). "TRPM7 knockdown significantly reduced HIF-1α protein level without change of HIF-1α gene transcription in androgen-independent prostate cancer cells insulted with hypoxia." (PMID 32215176, 2020).
prostate carcinoma (continued). "Transient receptor potential melastatin subfamily member 7 (TRPM7) was essential in the growth and metastatic ability of prostate cancer cells." (PMID 32215176, 2020). "Our previous study also found a higher level of TRPM7 expression in androgen-independent prostate cancer cells comparing with normal prostate cells." (PMID 32215176, 2020). "Our previous study revealed that TRPM7 expression increased in androgen-independent prostate cancer cells when compared with normal prostate cells." (PMID 32215176, 2020). "In prostate cancer, scientists reported that TRPM7 mediated-Mg2+ influx promoted the cell migration by inducing EMT, and TRPM7 suppression alleviated TGFβ-induced cell migration with a reduction of EMT markers." (PMID 32643506, 2020). "By utilizing the HPA database, the TRPM7 gene levels and the survival of prostate cancer patients were obtained." (PMID 32215176, 2020). "Next, TRPM7 protein expression was downregulated by using siRNA to determine if TRPM-mediated hypoxia-induced EMT change in androgen-independent prostate cancer cells." (PMID 32215176, 2020). "The subsequent study by other researchers also supported that TRPM7 played an essential role in the aggressiveness of prostate cancer." (PMID 32215176, 2020). "TRPM7 protein expression was significantly higher in metastatic prostate cancer tissues than that in benign prostatic hyperplasia tissues." (PMID 32215176, 2020). "Downregulation of TRPM7 inhibited migration and invasion of prostate cancer cells with a mechanism involved in the regulation of epithelial-mesenchymal transition (EMT)." (PMID 32215176, 2020). "When TRPM7 was activated by cholesterol, cell proliferation and migration of prostate cancer cells were increased." (PMID 32215176, 2020). "First, data mining was carried out to disclose the relationship between the TRPM7 gene level and the survival of prostate cancer patients." (PMID 32215176, 2020). "TRPM7 expression increased in prostate cancer cells regulating Ca2+ and Mg2+ influx, and thus leading to an increase of cell proliferation." (PMID 32215176, 2020). "This study investigated the role of TRPM7 in the metastatic ability of androgen-independent prostate cancer cells under hypoxia." (PMID 32215176, 2020). "The previous study demonstrated that TRPM7 protein expression was increased in metastatic prostate cancer tissues when compared with benign prostatic hyperplasia tissues." (PMID 32215176, 2020). "Further clinical research with a larger sample size is required to reveal the clinical value of TRPM7 in prostate cancer." (PMID 32215176, 2020). "TRPM7 inhibition by Carvacrol suppressed prostate cancer cells' proliferation, migration, and invasion." (PMID 32215176, 2020). "In contrast, blockage of TRPM7 increased TNF-related apoptosis-inducing ligand- (TRAIL-) induced apoptosis of prostate cancer cells." (PMID 32215176, 2020). "Exposure of astrocytes to TGF‐β1 induced gene expression of TRPM7 and a recent study described that TGFβ‐induced epithelial‐to‐mesenchymal transition in prostate cancer is mediated via TRPM7 expression (Sun, Schaar, Sukumaran, Dhasarathy, & Singh, 2018)." (PMID 30453391, 2019). "Increasing Ca2+ and Mg2+ influx promotes the proliferation of prostate cancer cells through activating TRPM7." (PMID 27803760, 2016). "In prostate cancer cells, knockdown TRPM7 by shRNA inhibited cholesterol-induced Akt or ERK phosphorylation." (PMID 27803760, 2016). "Activation of TRPM7 promotes prostate cancer cell proliferation, migration, and viability, while inhibition of TRPM7 by Gd3+ or 2-aminoethoxy diphenylborate (2-APB) enhances TRAIL-induced PC-3 cell apoptosis." (PMID 27803760, 2016). "- Increased Ca2+ to Mg2+ ratio in prostate cancer cells enhances TRPM7-mediated currents and promotes cellular entry of Ca2+, leading to increase in cell proliferation." (PMID 25079291, 2014). "The anti-apoptotic effect of TRPM7 has been demonstrated in prostate cancer cells." (PMID 38255793, 2024).
prostate carcinoma (continued). "Moreover, a higher Ca2+/Mg2+ ratio in prostate cancer patients resulted in increased Ca2+ influx mediated by TRPM7, which promoted cell proliferation." (PMID 38255793, 2024). "Furthermore, a recent study found that suppressing TRPM7 prevented hypoxia-induced malignant migration and invasion of androgen-independent prostate cancer cells via increasing RACK1-mediated HIF-1alpha degradation." (PMID 35771152, 2022). "The relationship between TRPM7 expression and survival of prostate cancer patients is unclear." (PMID 32215176, 2020). "Therefore, our findings reveal that Annexin A1 is a downstream molecular of TRPM7-HIF-1α signaling axis in prostate cancer under hypoxic conditions." (PMID 32215176, 2020). "It would be worthwhile determining in future experiments whether these factors also participate in EMT and invasion regulated by the TRPM7-HIF-1α signaling in prostate cancer under hypoxia." (PMID 32215176, 2020). "Besides, TRPM7 also mediated transforming growth factor beta- (TGF β-) induced EMT in prostate cancer." (PMID 32215176, 2020). "However, according to the instruction of HPA database, TRPM7 is still unable to consider as a prognostic gene of prostate cancer." (PMID 32215176, 2020). "Here, we presented that the result mining from the HPA database showed that when the best expression cutoff was used, a high level of TRPM7 gene expression in prostate cancer displayed poorer prognosis when compared with patients with low TRPM7 gene expression." (PMID 32215176, 2020). "Our study further lightens the role of TRPM7 in the tumor biology of prostate cancer." (PMID 32215176, 2020). "Therefore, current experimental research findings strongly indicated that TRPM7 played an oncogenic role in prostate cancer and likely served as a potential therapeutic target for cancer treatment." (PMID 32215176, 2020). "In the meantime, the results showed that hypoxia-induced EMT in androgen-independent prostate cancer cells along with increased TRPM7 expression, showing as hypoxia-induced significant decrease of E-cadherin (E-Cad) while an induced increase of expression of vimentin and N-cadherin (N-Cad)." (PMID 32215176, 2020). "It suggests the TRPM7-HIF-1α-Annexin A1 signaling pathway might serve as a potential drug target for the treatment of castrate-resistant prostate cancer." (PMID 32215176, 2020). "TRPM7 is a potential therapeutic target for treatment of prostate cancer." (PMID 27803760, 2016). "Hence, it suggests that both PI3K/Akt and MAPK signaling pathways are the downstream mechanisms of TRPM7 functions in prostate cancer." (PMID 27803760, 2016). "Furthermore, consistently, TRPM7 knockdown reduced prostate cancer cell proliferation, migration, and invasion as well." (PMID 27803760, 2016). "Our study suggests that carvacrol may have therapeutic potential for the treatment of prostate cancer through its inhibition of TRPM7 channels and suppression of PI3K/Akt and MAPK signaling pathways." (PMID 27803760, 2016). "However, it remains largely unknown about the role of TRPM7 in hypoxic signaling in prostate cancer." (PMID 32215176, 2020). "It remains unclear if TRPM7 expression was regulated by hypoxia in prostate cancer cells." (PMID 32215176, 2020). "It remains unclear in terms of the role of TRPM7 in the prognosis of prostate cancer patients." (PMID 32215176, 2020). "However, the effects and the relevant molecular mechanisms of TRPM7 on metastasis of prostate cancer under hypoxic atmosphere remain unclear." (PMID 32215176, 2020). "Thus, it has been suggested that Ca2+ influx through TRPM7 may be critical for fibroblast proliferation and a recent study on prostate cancer cells proposed that enhanced Ca2+ influx through TRPM7 determined their proliferation rate." (PMID 25277194, 2014). "Hypoxia increased TRPM7 expression and HIF-1α accumulation in androgen-independent prostate cancer cells." (PMID 38255793, 2024).
prostate carcinoma (continued). "Compared to normal prostate cells, the hormone-responsive and hormone-resistant prostate cancer cells overexpress CACNA1-D, TRPM-7, and TRPV-6." (PMID 38131032, 2023). "In this line, TGFβ stimulates the expression of TRPM7, further enhancing EMT in prostate cancer cells." (PMID 37762011, 2023). "Compared to nontumorigenic cells, the hormone-dependent cells overexpressed TRPM-7 and TRPV-6 and the hormone-resistant cells overexpressed CACNA1-D, TRPM-7, and TRPV-6, supporting the role of calcium channels in prostate cancer." (PMID 38131032, 2023). "Under hypoxia, the TRPM7-HIF1α-Annexin A1 signaling axis is essential for the EMT, cell migration and invasion of prostate cancer cells." (PMID 37762011, 2023). "We observed that Annexin A1 protein expression was increased by hypoxia in androgen-independent prostate cancer cells, which was inhibited by knockdown of both HIF-1α and TRPM7." (PMID 32215176, 2020). "Knockdown of TRPM7 significantly promoted HIF-1α degradation through the proteasome and inhibited EMT changes in androgen-independent prostate cancer cells under hypoxic condition." (PMID 32215176, 2020). "Reduction of HIF-1α, as well as downregulation of TRPM7, inhibited EMT and invasion of prostate cancer cells." (PMID 32215176, 2020). "Our result demonstrated that Annexin A1 served as a downstream target for TRPM7-HIF-1α signaling, contributing to the regulation of EMT change, migration, and invasion induced by hypoxia in androgen-independent prostate cancer cells." (PMID 32215176, 2020). "This study demonstrated that hypoxia increased TRPM7 expression and simultaneously induced HIF-1α accumulation as well as EMT in androgen-independent prostate cancer cells." (PMID 32215176, 2020). "Hypoxia simultaneously increased TRPM7 expression and induced HIF-1α accumulation in androgen-independent prostate cancer cells." (PMID 32215176, 2020). "Other TRP subfamilies have also been demonstrated in the cancer development, such as TRPM1 in melanoma, TRPM7 in human retinoblastoma cells and human head and neck carcinoma cells, TRPM8 and TRPV6 in prostate cancer." (PMID 23840757, 2013). "On the other hand, depletion of PRKAR2B, ADCK2, TRPM7, and TRIB2 significantly decreases the effect of TNFα on HIF-1α stability in osteosarcoma and prostate cancer cell lines." (PMID 22355351, 2012). "Moreover, it was observed that TRPM7-mediated Mg2+ influx stimulates EMT and promotes cell migration in prostate cancer cells, while RES impairs TRPM7 function, thereby impeding prostate cancer metastasis." (PMID 37345095, 2023). "TRPM7 silencing, however, significantly promoted hypoxia-inducible factor 1 alpha (HIF-1α) degradation through the proteasome and inhibited EMT changes in androgen-independent prostate cancer cells under hypoxic conditions." (PMID 33856653, 2021). "In prostate cancer cells PC3 and DU145, hypoxia-induced EMT resulted in increased levels of TRPM7, vimentin and N-cadherin, and decreased levels of E-cadherin, implying that TRPM7 expression was correlated with EMT." (PMID 34360952, 2021). "Moreover, suppression of TRPM7 abrogated HIF-1α/Annexin A1 signaling pathway to reduce hypoxia-induced EMT, cell migration, and invasion of androgen-independent prostate cancer cells." (PMID 32215176, 2020). "In this study, we investigated the effects of nonselective TRPM7 inhibitor carvacrol on cell proliferation, migration, and invasion of prostate cancer PC-3 and DU145 cells." (PMID 27803760, 2016). "Inhibition of TRPM7 enhances TNF-related apoptosis inducing-ligand- (TRAIL-) induced apoptosis in PC-3 cells, indicating that TRPM7 contributes to the pathogenesis of prostate cancer and serves as a potential therapeutic target for prostate cancer." (PMID 27803760, 2016).
prostate carcinoma (continued). "The accumulation of HIF-1, playing a central role in tumor progression, is regulated by TRPM7 through a non-conventional RelB-dependent nuclear factor kappa B (NFκB) signaling pathway and the regulation of superoxide activity in osteosarcoma and prostate cancer cell lines." (PMID 38255793, 2024). "Here, we proposed a hypothesis that TRPM7 might respond to hypoxia to regulate the degradation of HIF-1α, and thus to control its downstream target, Annexin A1, and subsequently to affect the hypoxia-induced aggressive ability of androgen-independent prostate cancer cells." (PMID 32215176, 2020). "Furthermore, both TRPM7 and HIF-1α knockdown significantly suppressed hypoxia-induced Annexin A1 protein expression, and suppression of HIF-1α/Annexin A1 signaling significantly inhibited hypoxia-induced cell migration and invasion of androgen-independent prostate cancer cells." (PMID 32215176, 2020). "In this study, we measured the expression of the L-type and T-type voltage-gated calcium channels, the nonselective cation channels TRPM-6 and TRPM-7, and the selective calcium channel TRPV-6 in nontumorigenic prostate cells and hormone-dependent and hormone-resistant prostate cancer cells." (PMID 38131032, 2023).